GCH1 (GTP cyclohydrolase 1)
Diseases named in the same sentence as GCH1 in open-access papers (continued):
Sharing a sentence is not in itself a finding about the gene and the disease.
diabetes (16 papers, 2012 to 2024). "Consistent with above results, diabetes caused decreases in wall thickness of the LV, fractional shortening, mitral E/A ratio, and ratio of GCH1/GAPDH and increases in LV internal diameters and IVRT 12 weeks after administration of STZ." (PMID 27295516, 2016). "Models of association of GCH1 gene polymorphisms with outcome variables, accounting for current smoking, kidney dysfunction* and diabetes duration covariates." (PMID 25369080, 2014). "Recently GCH1 has been linked to hypertension, atherosclerosis, diabetes, cardiac hypertrophy, and myocardial ischemia and has become a potential therapeutic target in cardiovascular disease." (PMID 22479495, 2012). "This study aimed to elucidate the anti-remodeling effects of empagliflozin (EMPA) in the presence of post-MI left ventricular systolic dysfunction, the interplay with diabetes status and the myocardial mechanisms underlying, by evaluating the involvement of GCH1 and the NOS pathway." (PMID 32782412, 2020). "De novo synthesis of BH4 is impaired due to low GTP cyclohydrolase-1 (GCH1) activity in diabetes and high glucose state." (PMID 39201524, 2024). "GCH1 alterations have been observed in chronic diseases such as diabetes, arthrosclerosis and hypertension and are implicated in PD." (PMID 39201524, 2024). "In PAD models with diabetes, excessive miR-133a in ischemic muscle or endothelial cells targeted GCH1 and reduced its protein level, which decreases NO synthesis and increases ROS production in the ischemic muscle tissue or endothelial cells." (PMID 29789398, 2018). "Taken together, the present study suggests that in PAD models with diabetes, miR-133a up-regulation inhibits NO-cGMP angiogenic pathway through targeting GCH1." (PMID 29789398, 2018). "These deleterious effects of diabetes were significantly attenuated by GCH1 overexpression (P < 0.05 between Tg STZ and WT STZ groups)." (PMID 27295516, 2016). "Our results indicated that GCH1 overexpression restored intracellular [Ca2+]i and SR Ca2+ content that were decreased by diabetes." (PMID 27295516, 2016). "This study deepens our understanding of impaired cardiac function in diabetes, identifies GCH1 as a modulator of cardiac remodeling and function, and reveals a new therapeutic target for diabetic cardiomyopathy." (PMID 27295516, 2016). "We showed that MG 132 diminished the degradation of cardiac GCH1 proteins and reduced cardiac dysfunction in diabetes." (PMID 27295516, 2016). "Intriguingly, either cardiomyocyte-specific overexpression of GCH1 or inhibition of the 26S proteasome with MG 132 preserved cardiac GCH1 proteins and diminished diabetes-induced cardiac remodeling and dysfunction." (PMID 27295516, 2016). "It is possible that decreased GCH1 proteins result from increased activity of 26S proteasome by diabetes." (PMID 27295516, 2016). "GCH1 overexpression decreased the expression of iNOS and O2•− levels in diabetes." (PMID 27295516, 2016). "It remains unknown how cardiomyocyte GCH1 is modulated in DCM, and whether cardiomyocyte-targeted increase of GCH1 proteins benefits intracellular Ca2+ signaling, thus improving cardiac function in diabetes." (PMID 27295516, 2016). "In the present study, GCH1 overexpression restored decreased RyR2-mediated Ca2+ release by diabetes, and the beneficial effects of GCH-1 overexpression on RyR2-mediated Ca2+ release were abrogated by S-methyl-L-thiocitrulline (SMTC, a specific inhibitor of nNOS)." (PMID 27295516, 2016). "However, increased ratio of iNOS/GAPDH by diabetes was significantly reduced by GCH1 overexpression." (PMID 27295516, 2016). "Whether cardiomyocyte-targeted increase of GCH1 proteins is capable of preventing NOS uncoupling in diabetes remains unclear." (PMID 27295516, 2016). "Furthermore, we found that MG 132, an inhibitor for 26S proteasome, preserved cardiac GCH1 proteins and ameliorated cardiac remodeling and dysfunction during diabetes." (PMID 27295516, 2016).
diabetes (continued). "Moreover, GCH1 overexpression attenuated myocardial interstitial fibrosis and apoptotic cardiomyocytes induced by diabetes." (PMID 27295516, 2016). "Interestingly, GCH1 overexpression significantly elevated the amplitude of the caffeine-induced [Ca2+]i transient in diabetes compared with WT STZ group (P < 0.05 between Tg STZ and WT STZ groups)." (PMID 27295516, 2016). "Interestingly, GCH1 overexpression eliminated diabetes-induced decreases in dimeric and phosphorylated nNOS and increases in iNOS but did not alter diabetes-induced reduction in dimeric and phosphorylated eNOS." (PMID 27295516, 2016). "Interestingly, GCH-1 overexpression abrogated these detrimental effects of diabetes." (PMID 27295516, 2016). "Thus, GCH1 overexpression is able to suppress oxidative stress in diabetes." (PMID 27295516, 2016). "Thus, improved intracellular Ca2+ signaling by GCH1 overexpression in diabetes may be mainly attributed to up-regualation of SR Ca2+ handling proteins." (PMID 27295516, 2016). "Interestingly, GCH1 overexpression reduced diabetes-induced remodeling and dysfunction of the LV." (PMID 27295516, 2016). "Therefore, GCH1 overexpression may exert favorable effect on RyR2-mediated Ca2+ release via nNOS in diabetes." (PMID 27295516, 2016). "Taken together, our results indicate that CT can obviously improve vascular endothelial injury in Type 1 diabetes mellitus (T1DM) rats and reverse the expressions of GCH1 and Smurf2 proteins in aorta of T1DM rats." (PMID 38993132, 2024). "In addition, the activation of cardiac GCH1 protein was a relevant mediator of myocardial beneficial effects of EMPA, by reducing oxidative stress in the presence of MI and/or diabetes." (PMID 32782412, 2020). "We also found that GCH1 overexpression increased the expression of RyR2 and SERCA2a proteins in nondiabetics and prevented diabetes-induced decreases in these two SR Ca2+ handling proteins." (PMID 27295516, 2016). "Diabetes-induced decrease in the ratios of eNOS dimers/monomers and p-eNOS/eNOS were not significantly changed by GCH1 overexpression (P > 0.05 between Tg STZ and WT STZ groups, n = 4 hearts/group)." (PMID 27295516, 2016). "In the present study, diabetes increased p-p38 MAPK, and the negative effect of diabetes on p38 MAPK was suppressed by GCH1 overexpression." (PMID 27295516, 2016). "The expression of cardiac GCH1 proteins was decreased by diabetes but the levels of GCH1 mRNA were not significantly altered." (PMID 27295516, 2016). "Since GCH1 mRNA levels were not changed, decreased GCH1 proteins by diabetes were not due to reduction of synthetic GCH1 rather than increased degradation of GCH1 proteins." (PMID 27295516, 2016). "Therefore, diabetes-induced decreases in GCH1 proteins resulted from their degradation rather than a decrease in their biosynthesis." (PMID 27295516, 2016). "Whether there is an interaction between cardiomyocyte GCH1 and p38 MAPK during diabetes is unknown." (PMID 27295516, 2016). "Thus, targeting myocardial metabolism in diabetic heart via BH4 could be beneficial, as we previously demonstrated in a cardiomyocyte‐specific Gch1 transgenic mouse, where augmentation of cardiomyocyte BH4 maintained cardiac function, glucose uptake and utilisation in diabetes." (PMID 37184360, 2023). "To study if GCH1 overexpression may reduce diabetes-induced impairments in intracellular Ca2+ signaling, we first measured intracellular [Ca2+]i in fura-2-loaded cardiomyocytes isolated from Tg and WT mice with or without diabetes 12 weeks after administration of STZ or vehicle." (PMID 27295516, 2016). "To study whether pharmacological approaches may preserve cardiac GCH1 proteins and diminish the severity of DCM, we used MG 132 to treat diabetic C57BL/6 mice for 8 weeks after 4 weeks of diabetes or nondiabetic C57BL/6 mice." (PMID 27295516, 2016).
Hypertension (13 papers, 2012 to 2026). The presence of chronic increased pressure in the systemic arterial system. "In pregnant mice, selective maternal endothelial BH4 deficiency resulting from targeted deletion of Gch1 caused progressive hypertension during pregnancy and fetal growth restriction." (PMID 34689592, 2021). "Genomic analysis of GCH1, which encodes GTPCH1, in humans found a sex-specific risk of hypertension in patients with a specific polymorphism of the GCH1 gene, with females having significantly higher BP than males and lower NO production." (PMID 29899168, 2018). "Our studies demonstrate the mechanism via which L-phe restores endothelial function in a model of hypertension, indicating that the GCH1-GFRP complex represents a viable therapeutic target for the restoration of endothelial function." (PMID 29963647, 2018). "The observation that inducible endothelial Gch1 deletion produces progressive hypertension in males and pregnancy-induced hypertension with fetal growth restriction in females underscores the context-dependent vulnerability of the endothelium to BH4 deficiency." (PMID 41031403, 2026). "Taken together, these observations indicate that endothelial cell GCH1 and BH4 regulate endothelial cell growth and tube formation and that reduced endothelial cell BH4 is a feature of pregnancy-induced hypertension and is associated with loss of endothelial cell NOS activity." (PMID 34689592, 2021). "In rescue experiments, high blood pressure and fetal growth restriction in pregnant endothelial cell Gch1 deficient mice was not rescued by oral BH4 supplementation, due to systemic oxidation of BH4 to dihydrobiopterin." (PMID 34689592, 2021). "It would now be important to establish the in vivo significance of our findings and to ascertain whether activation of the GCH1-GFRP axis could attenuate the development of hypertension in vivo in SHR and in the clinic." (PMID 29963647, 2018). "After establishing the role of vascular Gch1/BH4 biosynthesis in hypertension in response to Ang II, we next determined whether an endothelial cell-specific reduction in BH4 plays a specific and causal role in disease pathogenesis, rather than being a consequence of the disease." (PMID 29844152, 2018). "Our proof-of-concept study confirms that activation of GCH1-GFRP can directly affect vascular BH4, NO, and ROS and restore vascular function in a model of hypertension." (PMID 29963647, 2018). "Second, we studied mice with heterozygous Gch1 deletion in endothelial cells and found that these mice, despite a ≈50% reduction in endothelial BH4 levels, had normal prepregnancy BP and yet still developed hypertension in late pregnancy." (PMID 34689592, 2021). "Given the findings showing a requirement for endothelial cell Gch1 and BH4 in the responses to pregnancy in mice, we next sought to investigate whether endothelial GCH1 and BH4 are altered in pregnancy-induced hypertension in humans." (PMID 34689592, 2021). "To investigate whether Gch1/GTPCH protein and BH4 biosynthesis are modulated by Ang II–induced hypertension, we infused WT (C56BL6) mice with either saline or a pressor dose of Ang II at 1 mg/kg per day by osmotic minipump for 28 days." (PMID 29844152, 2018). "The aim of this study was to determine whether L-phe raises vascular BH4 levels by activating the GCH1-GFRP complex in vivo and improves endothelial function in an animal model of essential hypertension." (PMID 29963647, 2018). "We have discovered a new role for endothelial cell Gch1 and BH4 in the vascular adaptation and BP responses to pregnancy, with translational potential for treating the global health challenges of pregnancy-related hypertension, placental insufficiency, and fetal growth restriction." (PMID 34689592, 2021).
Hypertension (continued). "The absence of endothelial Gch1 deletion in offspring, which are conceived after the effects of tamoxifen administration, reinforces the role of maternal, rather than fetal, endothelial cell BH4 deficiency in pregnancy-induced hypertension and fetal growth restriction." (PMID 41031403, 2026).
Hyperphenylalaninemia (12 papers, 2012 to 2025). "WES analysis has shown that neither of these patients had pathogenic, likely pathogenic, or variants of uncertain significance (VUS) above 50% posterior probability in genes associated with hyperphenylalaninemia (GCH1, PCBD1, PTS, QDPR, SPR and DNAJC12)." (PMID 40473815, 2025). "In the current study, we examined the involvement of the GCH1 gene in pain models using the hyperphenylalaninemia 1 (hph-1) mouse, a genetic model for DRD, with only 10% basal GTP-CH1 activity compared to wild type mice." (PMID 23421753, 2013). "Homozygous GCH1 variants have been associated with two clinically distinct human diseases: hyperphenylalaninemia, and DRD with or without hyperphenylalaninemia." (PMID 36204308, 2022). "Autosomal recessive DRD that is associated with homozygous GCH1 variants should be considered in patients with severe truncal hypotonia, with or without diurnal fluctuation, even if there is an absence of limb dystonia and hyperphenylalaninemia." (PMID 36204308, 2022). "When no PAH variants are detected in a child with hyperphenylalaninemia, the genes for the various tetrahydropterin BH4 deficiencies are tested, such as GCH1, PTS, QDPR, and PCBD1." (PMID 38132826, 2023).
breast carcinoma (10 papers, 2016 to 2025). "Higher GCH1 levels are associated with lower breast cancer survival, indicating an enzyme-independent oncogenic role and positioning GCH1 as a potential therapeutic target." (PMID 41369326, 2025). "High expression of GCH1 in cancer-associated fibroblasts stimulates breast cancer cell proliferation and motility." (PMID 34513700, 2021). "To investigate the relationship of human GCH1 (the gene encoding GTPCH) expression with the prognosis of breast cancer patients, we analyzed expression in a series of 153 patients with complete follow-up and demographics as published previously." (PMID 26814432, 2016). "Second, the synergistic effects in vivo of GCH1 inhibitors with PARP inhibitors in breast cancer require more detailed exploration due to the limitations of the PDX model." (PMID 36793373, 2023). "Consistent with the RNA-seq results, GCH1 mRNA levels were increased in multiple ovarian and breast cancer cell lines in response to niraparib treatment." (PMID 36793373, 2023). "We observed that the core molecules of HRR cluster were mainly enriched in the GCH1-high expression group (P=0.04) in breast cancer." (PMID 36793373, 2023). "We previously demonstrated that overexpressing GCH-1 increased the BH4:BH2 ratio in MCF-7 breast cancer cells." (PMID 36998441, 2023). "In conclusion, we clarified that niraparib induced the upregulation of GCH1, which was associated with sensitivity to PARP inhibitors in ovarian cancer and breast cancer for the first time." (PMID 36793373, 2023). "Upregulation of GCH1 expression in breast cancer cells stimulates proliferation and growth of cancer cells, results in poor prognosis of breast cancer." (PMID 36505465, 2022). "According to the results, GCH1 exhibits relatively higher expression levels in the liver, endometrium and breast cancers than the tumor adjacent tissues." (PMID 34513700, 2021). "Furthermore, logistic regression analysis revealed the statistically significant association between GCH1 high expression and histological type, PR status, ER status, and HER2 status in breast cancer." (PMID 36793373, 2023). "Thus, we treated ovarian and breast cancer cell lines with GCH1 inhibitor DAHP and analyzed γ-H2AX foci formation." (PMID 36793373, 2023). "Interestingly, on the orthotopic breast cancer model (E0771 cells), the tumor growth was rejected in GCH1-overexpressing mice." (PMID 34502450, 2021). "To study the link between GCH1 and Ang-1 in a tumor stromal compartment-specific manner, we analyzed their transcript levels in a public data set of human gene expression arrays from breast cancer stroma (Accession numbers: GSE9014)." (PMID 26814432, 2016). "Furthermore, high GCH1 in tumor stroma was significantly correlated with the phenotype of ER-breast cancer." (PMID 26814432, 2016). "Given the Spearman correlation coefficients were 0.53 and 0.58, GCH1 and STAT1 were well-correlated in breast cancer and ovarian cancer." (PMID 36793373, 2023). "Surprisingly, STAT1 ranked first in both breast cancer and ovarian cancer, implying that there might be a strong correlation between STAT1 and GCH1." (PMID 36793373, 2023). "Moreover, we clarified that the suppression of GCH1 could sensitize tumor cells to the PARP inhibitor, in order to better ameliorate clinical management of ovarian and breast cancers." (PMID 36793373, 2023).
glioblastoma (10 papers, 2019 to 2026). The most malignant astrocytic tumor (WHO grade IV). "The role of GCH1 in cancer is highly controversial: GCH1 promotes the progression of gastric cancer, glioblastoma and triple-negative breast cancer by influencing proliferation and metastasis as well as the TME 27-29." (PMID 41583517, 2026). "Consistent with our results, GCH1 was also upregulated in glioblastoma, indicating its potential hub role in tumorigenesis." (PMID 36793373, 2023). "Previous research has demonstrated that PRRX2 functions as a transcription factor and may exert transcriptional regulatory effects on GCH1, which plays a crucial role in mediating ferroptosis in glioblastoma." (PMID 39434056, 2024). "Furthermore, our previous study showed that circLRFN5 inhibits the progression of glioblastoma through the PRRX2/GCH1-mediated ferroptosis." (PMID 37723588, 2023). "In glioblastoma (GBM), in silico analyses showed that increased GCH1 expression was correlated with higher glioma grade, recurrence, and worse survival." (PMID 34502450, 2021). "Contrasting with these oncogenic circRNAs, circLRFN5 exhibits tumor-suppressive properties in glioblastoma (GBM) by promoting ubiquitin-mediated degradation of PRRX2, a transcriptional activator of GCH1." (PMID 40403492, 2025). "This process is predominantly mediated through the GCH1/BH4 signaling pathway, aligning with prior findings in glioblastoma research." (PMID 39434056, 2024). "We recently defined a role for GTP Cyclohydrolase I (GCH1), the first and rate limiting enzyme in the tetrahydrobiopterin (BH4) pathway, as an important regulator of glioblastoma growth." (PMID 31500569, 2019).